MMP11 (matrix metallopeptidase 11)
Diseases named in the same sentence as MMP11 in open-access papers (continued):
Sharing a sentence is not in itself a finding about the gene and the disease.
cancer (continued). "Consistent with it, we found exosomal miR-139 downregulated MMP11 in CAFs, inhibiting cancer cells migration, and further inhibited metastasis of GC cells." (PMID 31595150, 2019). "For example, they are inhibited by gemcitabine (RRM2), marimastat (MMP9 and MMP11) for treating several cancers." (PMID 30729033, 2019). "Our analysis supports a theory that MMP-11 expression is critical in cancer development and progression." (PMID 31200666, 2019). "Aside from KIRP and PRAD for MMP13, and KICH and UCEC for MMP11, the upregulation was consistent across all cancer types." (PMID 31200666, 2019). "The overexpression of many MMP family members, such as MMP2, MMP9 and MMP11 has been found to be involved in cancer progression 27-29." (PMID 31595150, 2019). "Upregulated in 13 of 15 cancer types, MMP11 expression differences yielded particularly high fold changes and high AUCs." (PMID 31200666, 2019). "This upregulation of MMP11 was contrasted by other MMPs where up-regulation was more cancer-type specific." (PMID 31200666, 2019). "Although MMP1 and MMP2 are well-known regulators of cardiac ECM components, MMP11 has been observed in endometrium and human carcinomas." (PMID 31513610, 2019). "In vivo, MMP-11 was shown to promote cancer progression by remodeling the extracellular matrix and downregulation of MMP-11 by siRNA attenuated cancer metastasis." (PMID 28915700, 2017). "Our data reveal a major role for MMP11 in controlling energy metabolism, and provide new clues for understanding the relationship between metabolism, cancer progression and patient outcome." (PMID 27126782, 2016). "On the other hand, the levels of MMP11 in all the 3 cancer tissues were elevated compared with that in normal tissue." (PMID 26084486, 2015). "As a member of the MMPs family, MMP-11 has long been postulated to play an important role in tumorigenesis, invasion, metastasis and poor clinical outcome in malignant tumors." (PMID 26507719, 2015). "The overexpression of many MMP family members, such as MMP1, MMP2, MMP7, MMP9, and MMP11 has been found to be involved in cancer progression; therefore, the development of MMP inhibitors has become an effective strategy in clinical cancer therapies." (PMID 26084486, 2015). "In their research, MMP-11 favors the onset and growth of lung metastasis but limiting lung foci number, and inhibiting the cancer cell dissemination to other organs." (PMID 26507719, 2015). "Together with our results, plasma concentration of MMP-11 protein appears to be a promising candidate biomarker for various human cancers and deserves clinical verification by further studies." (PMID 25423087, 2014). "Of particular interest, MMP11 (0.47-fold and 0.37-fold at 10 nM and 100 nM, respectively), which is involved in the “Cell Death, Cellular Growth and Proliferation, Cancer” network, was shown to be down-regulated." (PMID 22574217, 2012). "Previously, we demonstrated that MMP-11 was a cancer-related protein and its over-expression was consistently confirmed at mRNA and protein levels in primary gastric adenocarcinoma tumors compared with matched normal tissues." (PMID 21513571, 2011). "Three types of cancers are covered by 22 2-gene combinations, with MMP11+RRM2 and MMP7+MMP9 representing the top 2-gene markers with at least 75% classification accuracy." (PMID 21060876, 2010). "Stromelysin 3 ST3 (MMP-11) is another protease that can modulate cancer progression by remodelling extracellular matrix." (PMID 15989693, 2005). "MMP-9 (92 kDa gelatinase) and MMP-11 (stromelysin 3) were most consistently expressed by carcinomas." (PMID 8645587, 1996). "Finally, the expression pattern and prognostic value of MMP11 in tumors were explored based on pan-cancer data." (PMID 40607407, 2025). "Furthermore, the study revealed the widespread presence of MMP11+ mCAFs across multiple cancer types, offering a novel potential therapeutic target for cancer treatment." (PMID 40552583, 2025).
cancer (continued). "The presence of MMP11 could exacerbate endoplasmic reticulum stress, alter the mitochondrial unfold protein response, which mediated cancer progression." (PMID 38572434, 2024). "Most studies concur that MMP-11 overexpression correlates with a poor prognosis in cancer cases." (PMID 38438841, 2024). "MMP-11 participates in tissue remodeling processes, including those related to cancer progression." (PMID 38203373, 2023). "Currently, research confirms that MMP-11 may be a prognostic factor for detecting early-stage cancer." (PMID 38203373, 2023). "The immunotherapeutic role of MMP11 in different cancers has been suggested previously." (PMID 36683048, 2023). "MMP11 has been suggested as a novel target antigen for cancer immunotherapy." (PMID 37238942, 2023). "Distinct roles of MMP11 in cancer development, progression and therapeutics have been reported." (PMID 37238942, 2023). "Currently, there is a belief that MMP-11 promotes cancer development." (PMID 38203373, 2023). "Matrix metalloproteinase 11 (MMP11) functions as a key driver of cancer development and metastasis." (PMID 35127685, 2022). "MMP-11 is a negative prognosis marker in several human cancers and can also cause delipidation of adipocytes." (PMID 36551185, 2022). "Hence, MMP11 expression in BCC is responsible for ectodomain shedding of biologically active sCD200 from cancer stem cells into the surrounding TME." (PMID 36074574, 2022). "A representative marker of ECM and cancer invasion, MMP-11, was elevated in the presence of CAFs." (PMID 34408230, 2021). "Recent studies have suggested that MMP-11 may be a good candidate target for cancer immunotherapeutic treatment." (PMID 34038440, 2021). "MMP-11 may enhance cancer development and progression by proteolytic degradation of the endothelial basement membrane." (PMID 34038440, 2021). "Indeed, a large number of previous studies have shown that MMP11 functions as an oncogene in a variety of cancers." (PMID 33836753, 2021). "We also observed an increased expression of some metalloproteinases such as MMP14 and MMP2, which are known mediators of cancer invasion and a remarkable decrease of two metalloproteinases, MMP11 and MMP12, which are known to have a protective role against tumors." (PMID 34680461, 2021). "Also, our results revealed that MMP-11 expression was higher in primary cancer than normal breast tissue." (PMID 34038440, 2021). "In addition, the CP2E pattern was characterized by cancer-associated myofibroblasts expressing potential novel therapeutic targets, such as PSTN and MMP11." (PMID 34663877, 2021). "Taken together, these data suggest that MMP11 overexpression confers an advantage for cancer cells to promote their growth through a metabolic reprogramming involving an increase in aerobic glycolysis, a decrease in mitochondrial respiration, and an increase in lipid turnover." (PMID 32825455, 2020). "How the metabolic role of MMP11 contributes to cancer development is poorly understood." (PMID 32825455, 2020). "In summary, the inhibition of MMP11 may become an intervention method for the treatment of malignant tumors." (PMID 32291953, 2020). "MMP-11 expression has been demonstrated to be upregulated in the serum and solid tumor tissues of patients with different types of cancer, such as non–small cell lung cancer, esophageal carcinoma, pancreatic carcinoma, ovarian carcinoma, colon cancer, and oral cancer." (PMID 33228130, 2020). "A reason for this pan-cancer upregulation might be related to the functional ability of MMP-11 in helping evade immune surveillance by desensitizing cancer cells to NK-cells." (PMID 31200666, 2019). "In this study, we found MMP11 in exosomes of CAFs promoted cancer cell migration." (PMID 31595150, 2019). "Matrix metalloproteinase-11 (MMP-11) has been observed in most invasive human carcinomas." (PMID 28427180, 2017).
cancer (continued). "Like many other members of MMPs, increased expression of MMP-11 has been observed in most invasive human carcinomas, including lung, breast, colorectal and ovarian carcinomas, and high levels of its mRNA was reportedly associated with aggressive phenotypes and poor clinical outcome." (PMID 28427180, 2017). "Thus, invasive cancer cells induce proximal adipocytes to express MMP11 leading to their dedifferentiation into fibroblasts [reviewed in18]." (PMID 27126782, 2016). "MMP11 also participates in human diseases, most notably cancers." (PMID 27126782, 2016). "Given that MMP11 is overexpressed in almost all invasive cancers, we speculate that the effect of MMP11 overexpression observed in the adipose tissue of Mmp11-Tg model could recapitulate the metabolic changes observed in CAAs and CAFs19." (PMID 27126782, 2016). "On the other hand, neighboring cancer cells may reprogram adipocytes into fibroblast-like cells to promote expression of MMP11 and cancer cell survival and invasion." (PMID 27409168, 2016). "Our data provide a rationale for the deleterious effects of MMP11 on human carcinomas." (PMID 27126782, 2016). "MMP11 overexpression is a bad prognostic factor in various human carcinomas." (PMID 27126782, 2016). "These unique properties indicate that MMP-11 might play some unique roles in malignant tumor development and progression." (PMID 26507719, 2015). "MMP-11 plays a role in embryonic implantation, organ ontogenesis, tissue involution, repair processes 2,3, and numerous diseases like atherosclerosis, rheumatoid arthritis, and cancers 4,5." (PMID 25081520, 2014). "Matrix metalloproteinase-11 (MMP-11) is reported to be overexpressed in several cancers and may contribute to tumorigenesis." (PMID 25423087, 2014). "This could be very important in malignant conditions since MMP-11 was shown to play an essential role during the early steps of cancer cell invasion of adjacent connective tissues 1,5,6." (PMID 25081520, 2014). "The MMP-11 is a protease that can modulate cancer progression by remodelling extracellular matrix." (PMID 20160732, 2010). "Interestingly, MMP9 and MMP2 up-regulation in cervical cancer was previously reported and the combined overexpression of MMP9, MMP11 and TIMP1 has been associated with the invasive features of some cancers." (PMID 15989693, 2005). "MMP11 expression has been reported in pre-invasive bronchial lesions and in carcinomas." (PMID 15989693, 2005). "Both of these subtypes shared characteristics of myofibroblast cancer-associated fibroblasts (mCAFs) because of the high level of expression of the genes encoding extracellular matrix building, i.e., COL4A1; ECM remodeling proteins, i.e., MMP11; and contractile proteins, i.e., TPPP3 and MYL9." (PMID 39796089, 2024). "Therefore, tumorigenesis caused by high expression of MMP-11 did not result from increased cancer cell proliferation, but from decreased cancer cell death through apoptosis and necrosis." (PMID 34038440, 2021). "However, carcinoma samples with MMP-11 positive MICs showed a more important increase in the mRNA level of 19 factors: IL-1, −5, −6, −8, −17 and −18, ADAM-8, −10, −15, and −23, ADAMTS-1, −2, and −15, IFNβ, MMP-1, as well as mediators related to inflammation (CCL-3, IRAK-4, MyD88 and NFκB)." (PMID 23145063, 2012). "The MMP11 gene belongs to a family of matrix metalloproteinases, proteolytic enzymes that degrade extracellular matrix and promote the local or metastatic potential of carcinoma cells, and whose action is restrained by special inhibitors (metalloproteinase inhibitors)." (PMID 18793406, 2008). "Thus it suggests that MMP-11 may play a regulatory role in the invasion and metastasis of carcinomas." (PMID 8645587, 1996).
cancer (continued). "A CAF subpopulation which highly expressed extracellular matrix (ECM) remodeling genes (MMP11, CTHRC1 and COL1A2) was annotated as matrix CAF (mCAF), resemble the previously reported mCAFs in cancer data." (PMID 39703515, 2024). "Knockdown of PLK3 inhibited expression of MMP11 and SNAI2, known players in the regulation of cancer invasion and metastasis." (PMID 38169509, 2024). "Among them, only six genes—MMP11, ANGPTL1, GSTM5, IQGAP3, UHRF1, and CCBE1—were shared across all analyzed carcinomas." (PMID 39596491, 2024). "Most MMPs have consistently increased gene expression across cancers, and MMP1, MMP9, MMP10, MMP11, and MMP13 are almost universally upregulated across a wide variety types of cancers." (PMID 36903626, 2023). "MMP, such as MMP11 and MMP14, are involved in degrading the ECM in various cancers and therefore promote metastasis and angiogenesis." (PMID 36587397, 2023). "Similar types of MMPs were found to be increased in both cancers, namely, MMP-1, MMP-2, MMP-9, and MMP-11." (PMID 36982551, 2023). "Aiming to validate the gene expression, we evaluated the protein expression of MMP11 due to its known role in cancer progression and its possible role in predicting ADT response in both cultured CAFs and cancer tissues from radical prostatectomy." (PMID 35885510, 2022). "The majority of MMPs and TIMPs were mainly expressed in cancer cells at the invasive front (MMP-9: 97.3% of the tumors, MMP-11: 98.7%, MMP-14: 94.0%, TIMP-1: 86.7%, TIMP-2: 96.7%)." (PMID 33669393, 2021). "Expression levels of MMP2 and MMP14 were similar in both tissue types; MMP3 protein expression was lower in para-cancer tissues than in HCC tissues; MMP11 protein expression was higher in HCC tissues." (PMID 34376644, 2021). "Three clinically significant and highly studied genes were selected as target genes for each cancer type: HERE2, MYBL2, and MMP11 for BRCA and NOTCH2, BRCA1, and PDC for COAD." (PMID 34422018, 2021). "The gene set enrichment analysis revealed that these interacting proteins also interacted with cancer-related proteins, including KISS1, TIMP2, MMP11, IGFBP1, EGFR, and CDKN1C." (PMID 32117443, 2020). "In this study, real-time polymerase chain reaction was used to analyze five SNPs of MMP11 rs738791, rs2267029, rs738792, rs28382575, and rs131451 in 431 patients with UCC and 650 cancer-free controls." (PMID 31940762, 2020). "MMP11 and MMP13 expression was dramatically higher in most cancer types compared to tissue matched controls." (PMID 31200666, 2019). "MMP11 expression was comparatively high in the normal UCEC tissue, while the other non-significant pairs retained relatively low expression within the cancer samples." (PMID 31200666, 2019). "MMP1, MMP9, MMP10, MMP11, and MMP13 were almost universally upregulated across all cancers, with significant (p < 0.05) fold change (FC > 2) in ten of fifteen cancers." (PMID 31200666, 2019). "Seven MMPs (MMP7, MMP11, MMP12, MMP13, MMP24, MMP27, and MMP28) had an AUC of greater than 0.95 for at least one cancer type." (PMID 31200666, 2019). "Several triple-evidenced genes (MMP9, MMP11, CXCL12, MYL9) appear in three out of the five significantly enriched pathways and in more than half of the 13 cancers." (PMID 30729033, 2019). "Cancer fibroblast and stromal cells had increased expression of MMP and MMP-related genes: MMP2, MMP11 and TIMP1." (PMID 30383866, 2018). "Each guide strand and passenger strand coordinately regulates oncogenic genes as observed in several cancers, e.g., pre-miR-145: MTDH and UHRF1; pre-miR-139: MMP11; pre-miR-150: SPOCK1." (PMID 28902136, 2017). "From various cancer formation and metastasis signals, it can be seen that a set of matrix metalloproteases (MMPs) (MMP27, MMP23B, THBS2, MMP13, MMP11) as well as the MMPs receptor ITGB3 were inhibited in GX0101-infected CEFs." (PMID 27200301, 2016). "In particular, MMP11 and HPSE2 were closely examined due to the important roles they play in cancer cell growth and migration." (PMID 26084486, 2015).
cancer (continued). "Interestingly, there might also be a dual role of MMP-11 in cancers." (PMID 26507719, 2015). "MMP-11 (stromelisin-3 or ST3) and MMP-19 are important in cancer cell proliferation and demonstrated the opposite roles in studies of genetic mouse models." (PMID 25352026, 2015). "In addition, pan-dCAFs expressed high levels of COL11A1, COL1A1, MMP11 and MMP1, which are closely related to cancer invasion." (PMID 38827236, 2024). "Its interaction with diverse molecular targets such as ALK4, MMP11, and STAT3 points out a complex network of regulatory mechanisms that may exhibit variable behaviors across different cancer types and stages." (PMID 38872210, 2024). "Among the different CAF subtypes, MMP-11 mRNA was detected in myCAF, a subpopulation enriched in myofibroblasts markers, much less in immunomodulating CAFs, and not in cancer cells." (PMID 38438841, 2024). "Similar types of MMPs are increased in both cancers, namely, MMP-1, MMP-2, MMP-9, and MMP-11." (PMID 36982551, 2023). "With respect to the genes having interaction(s) with miRNAs, we realized four down-regulated vDEGs (TMEM100, MYH11, CHRDL1, and FAM107A) to the accompaniment of five up-regulated vDEGs (KLK10, CLDN1, SLC6A6, MMP11, and SLC7A5) being documented by the GEPIA in both COAD and READ cancer types." (PMID 35333898, 2022). "The cancer genes are composed of genes that code for HER2 (HER2 and GRB7), oestrogen genes (ER, PGR, BCL2, and SCUBE2), proliferation genes (MKI67, STK15, BIRC5, CCNB1, and MYBL2), and invasion genes (MMP11 and CTSL2) as well as GSTM1, CD68, and BAG1." (PMID 36042999, 2022). "Given the role of SP1 in responding to DNA damage — which would be present in both UVB-irradiated cells and cancer — we hypothesized that SP1 might directly mediate the induction of Mmp2 and Mmp11 mRNA by UVB." (PMID 35316219, 2022). "MMP11 expression in BLCA is significantly higher than that in normal bladder tissues, and MMP11 expression is positively linked to an aggressive cancer subtype and a poor prognosis in BLCA." (PMID 35450397, 2022). "In this study, we use real-time polymerase chain reaction to analyze five SNPs of MMP11 rs738791, rs2267029, rs738792, rs28382575, and rs131451 in 431 patients with UCC and 650 cancer-free controls, and try to elucidate their correlations in UCC development and clinicopathological characteristics." (PMID 31940762, 2020). "On the other hand, in animal models, MMP-11 plays a negative role against cancer development via the suppression of metastasis." (PMID 33419373, 2020). "This study showed that MMP11 mediates a metabolic switch to aerobic glycolysis at the expense of oxidative phosphorylation in the absence of cancer." (PMID 32825455, 2020). "For example, cancer cells stimulate expression of adipokines and adipocytokines (including IL-6, IL-1β, CCL2, CCL5, TNF-α, MCP-1, leptin), proteases, and inhibitors (e.g., MMP-11, PAI-1)." (PMID 28101337, 2017). "Interestingly, most of these genes (25 genes) were down-regulated, and only 3 genes (COL10A1, MMP11, and TUBB3) were up-regulated in cancer tissues." (PMID 26084486, 2015). "The association of genetic polymorphisms in the MMP-11 and MMP-19 with cancer risk has not been investigated; only the results of MMP-19 expression have been described as associated with cancer processes." (PMID 25352026, 2015). "Plasma levels of MMP-11 protein were not correlated with age, sex, smoking, drinking, betel nuts chewing, cancer location, distant metastasis and cell differentiation." (PMID 25423087, 2014). "In conclusion, our study, albeit preliminary, further suggest that MMP11 may act as a bona fide TAA and be a suitable target for cancer immunotherapy." (PMID 24564996, 2014). "It has been previously reported that when MMP11 is increased in tumorigenesis, this is not due to increased neoangiogenesis or cancer cell proliferation, but from a decrease of cancer cell death by apoptosis and necrosis." (PMID 15989693, 2005).